S100A8 (S100 calcium binding protein A8)
Diseases named in the same sentence as S100A8 in open-access papers (continued):
Sharing a sentence is not in itself a finding about the gene and the disease.
tumor (continued). "To provide further evidence on the conclusion that CCL5 suppresses CD8+ T cells accumulation via secreting S100a8/a9, we examined the correlation between the expression level of CCL5 and S100a8/a9 and the number of CD8+ T cells infiltrated in the tumor of CRC patients." (PMID 29991744, 2018). "S100A8 is highly expressed in the cytosol of some immune cells including neutrophils, macrophages, and dendritic cells, and is induced by toll-like receptor (TLR) agonists, and S100A9 inhibits myeloid differentiation thereby contributing to tumor growth." (PMID 29897930, 2018). "However, these processes are only consecutive to tumor-mediated immune reprogramming and activation in distant tissue and therefore dependent on CCL2/CCR2 driven S100A8/A9 release." (PMID 28744322, 2017). "Further research is also needed to determine when changes in S100A8/A9 and S100A12 could possibly occur along the spectrum of tumor development and whether these tests can detect pre-cancerous pathology or early cancer." (PMID 28431528, 2017). "We found increased S100A8/A9 levels in lungs of 4T1.2-tumor bearing mice as early as ten days after tumor inoculation when no local metastatic deposit of tumor cells was evident." (PMID 28744322, 2017). "We had previously shown that myeloid cells suppressed ANGPTL7 expression in cancer cells, leading to decreased tumor cell proliferation, and in keeping with this, S100A8 or S100A9 knockdown did not alter ANGPTL7 mRNA levels." (PMID 27086923, 2016). "Interestingly, gene expression profiles of tumor associated MP and MG were similar with a few exceptions like S100A8/9 and MMP9 which were down regulated in tumor MP." (PMID 27936099, 2016). "Monocytes/macrophages from tumor-bearing livers, but not normal livers, expressed high levels of TNFα and stimulated S100a8 and S100a9 expression." (PMID 27086923, 2016). "Interestingly, 4 of the top 5 up-regulated proteins in tumor TIF were all S100 family members, including S100P (ratio = 40.9), S100A9 (ratio = 19.0), S100A8 (ratio = 5.3) and S100A12 (ratio = 4.5)." (PMID 27216119, 2016). "While we demonstrate the effects mediated intracellularly through alterations in calcium levels, tumor-derived S100A8 and S100A9 are likely to have other effects both intracellular and/or extracellular in the tumor microenvironment, both in our model and in other tumor settings." (PMID 27086923, 2016). "S100a8 and S100a9 are ligands for Ager (advanced glycation end-product receptor), another PPAR-dependent gene that mediates acute and chronic inflammation, tumor development, and metastasis in several types of cancer and proliferative disorders, including gastric carcinogenesis and psoriasis." (PMID 28077942, 2016). "Several lines of evidence point to vital functions of S100A8 during tumorigenesis and, although it’s exact role within the tumor microenvironment is still not clear, different tumor-promoting effects have been proposed." (PMID 25789858, 2015). "Higher levels of ARG1, iNOS, S100A8 and S100A9 in CD11b+Gr-1 + cells from Lewis- and B16- tumor bearing mice could be detected as compared to the counterparts from tumor-free mice." (PMID 26285119, 2015). "Both S100a8 homodimers and calprotectin signal via Toll-like receptor-4 (Tlr4), consistent with expression of Tlr4 in all four tumour lines (data not shown)." (PMID 25633981, 2015). "However, in SCC12 cells, overexpressing S100A8 and/or S100A9 had increased proliferation and cell migration capacity in vitro and also showed increased tumor growth in vivo in SCID mice." (PMID 26053695, 2015). "Furthermore, S100A8 and S100A9 are expressed by HCC tumour cells as well as by other tumours of epithelial origin including lung, breast, gastric, and prostate." (PMID 24333183, 2014). "Endothelial-cells-derived inflammatory chemotaxins S100A8 and S100A9 induced by distant primary tumor may attract Mac1 (macrophage antigen 1) (+)-myeloid cells to the premetastatic site to promote tumor growth in the lung." (PMID 24587996, 2014).
tumor (continued). "The levels of calcium binding proteins S100A8 and S100A9 increase in cancer, including PDAC; although mainly expressed by tumor-infiltrating inflammatory cells, they may also be expressed by PDAC cells." (PMID 24670043, 2014). "We performed immunohistochemical (IHC) staining to detect the expression of S100A8 and S100A9 in sections of 42 pairs of samples (CRC and matching distal normal tissues) and found that S100A8 and S100A9 were elevated in tumor cells of CRC tissues compared with the matching distal normal tissues." (PMID 23637971, 2013). "Take together, our results provide important information regarding the roles of S100A8 and S100A9 in malignancy and should be paid much attention considering that S100A8 and S100A9 has been increasingly recognized as tumor markers and also as new molecular targets for developing cancer therapeutics." (PMID 23637971, 2013). "The same study showed that up-regulation of S100A8 and S100A9 by tumor- derived factors might represent one major mechanisms by which abnormal DC differentiation is established in cancer." (PMID 23166536, 2012). "Through the production of VEGFA, TGFβ, and tumor necrosis factor-α (TNFα), tumor cells enhance the expression of the chemoattractants S100A8 and S100A9 in lung endothelium and myeloid cells, which in turn promote tumor cell homing and adhesion to the metastatic site." (PMID 22482059, 2012). "The S100A8 and S100A9 proteins are RAGE ligands, DAMPs, markers of myeloid-derived suppressor cells, GM-CSF induced cytokines in eosinophils, and tumor promoting factors in experimental models." (PMID 22251275, 2012). "S100A8, a calcium-binding protein that complexes with S100A9 and whose expression is suppressed by functional BRCA1, is induced by H-Ras to promote malignant potential (tumor cell invasion and migration)." (PMID 21627793, 2011). "Blocking S100A8 and S100A9 expression in the premetastatic stage could prevent this permissive niche from being formed and thus inhibit the migration of tumor cells." (PMID 19292913, 2009). "S100A8 and S100A9 are chemoattractant proteins that can promote the recruitment of immune-suppressive immune cells into tumor niches, and their detection here may therefore be consistent with this notion." (PMID 19536297, 2009). "Several genes thought to play a role in the processes of invasion, tumour progression and metastasis (MME, STAT3, DCBLD2, S100A10, CD9, S100A8) were highly downregulated in the NE vs the non-NE tumour group." (PMID 18827820, 2008). "Expression of S100A8 was strongly induced in both normal‐like cell lines but could not be measured in the tumor cell lines." (PMID 40170512, 2025). "Furthermore, an integrated evaluation of S100A8 expression in both the tumor and immune compartments of EC has not yet been reported." (PMID 41303754, 2025). "Interestingly, extracellular S100A8 was found to negatively regulate this axis, suggesting a potential autocrine feedback mechanism that modulates the strength of TGF-β signaling in the tumor microenvironment." (PMID 40806457, 2025). "Notably, TGFB1, TGFB2, TGFB3, S100A8, S100A9, IL6, and PTGES secreted by PMN-MDSCs exhibit both protumorigenic and immunosuppressive properties, playing significant roles in promoting tumor growth and evading immune responses." (PMID 41280721, 2025). "C1 S100A8+ TCs acted on myeloid cells CD74-CXCR4 and CD74-CD44 receptors through MIF ligands, which might promote the transformation of normal myeloid cells into cancer-related myeloid cells and inhibit the body’s normal anti-tumor immune effect." (PMID 39691708, 2024). "S100 family members S100A8/A9 facilitating the migration of monocytes and neutrophils are capable of inducing pro-inflammatory cytokines in monocytes and macrophages via the NF-κB and p38 MAPK pathways, thus promoting migration and invasion of tumor cells through Akt and p38 MAPK signaling." (PMID 39232806, 2024).
tumor (continued). "The secretion of S100A8 and S100A9 by M-MDSCs might provide positive autocrine feedback loop that ensures the maintenance of functionally suppressive MDSCs within an inflammatory tumor environment." (PMID 38304256, 2023). "Among tumors with ≥ 10% S100A8 + tumor epithelial cells, we found 4/268 (1%) Luminal A, 2/116 (2%) Luminal B, and 1/36 (3%) Luminal B (HER2+) tumors, whereas we found 8/28 (29%) HER2, 3/12 (25%) 5NP, and 12/35 (34%) BP tumors expressed S100A8 in ≥ 10% of tumor epithelial cells." (PMID 37450087, 2023). "We detected 24 genes across the tumor tROIs that showed a high CV (i.e., were among the genes with the top 20% highest CV in seven out of seven cases), such as multiple collagens (COL1A1, COL1A2, COL3A1, COL5A1, COL5A2), S100A8, S100A9, FN1, or Early growth response protein 1 (EGR1)." (PMID 37511126, 2023). "Furthermore, the relationship between infiltrating S100A8 + immune cells and increased S100A8 copy number (CN) or S100A8 expression in tumor cells has not been described in detail." (PMID 37450087, 2023). "Additionally, S100A8 can induce T-cell immune tolerance in specific tumor-bearing microenvironments, but no relevant studies have been able to demonstrate an effect of S100A8 on CD8+ T-cell chemotaxis and function." (PMID 36906583, 2023). "After release, S100A8/A9 block the differentiation of MDSCs into DCs, leading to an increase in MDSCs,150 further promoting MDSC accumulation and thus coordinating the formation of an immunosuppressive microenvironment conducive to tumor growth in premetastatic tissues." (PMID 37547175, 2023). "S100A8/A9/RAGE axis activation act as a novel pro-inflammatory signaling cascade in prostate, breast, and pancreatic cancers, triggering multiple downstream pro-inflammatory signaling pathways within the TME, thus promoting tumor cell survival, progression, and metastasis." (PMID 35727208, 2022). "Interestingly, signal transduction proteins S100A8 and S100A9 upregulated in exosomes of poor responders were previously proposed as CRC tumor-specific exosomal markers, involved in migration, leucocyte recruitment, tumor-promoting inflammation, and formation of premetastatic niches." (PMID 35205741, 2022). "However, in animal models of breast cancer with brain metastases, CD11b-positive myeloid cells have been found to aggregate and form the “soil” for early tumor metastasis; this further releases the inflammatory factors S100A8 and S100A9, inducing tumor cell chemotaxis." (PMID 36338717, 2022). "Moreover, MDSCs-produced cytokines and chemokines, such as TGF-β, VEGFA, S100A8/A9, and MMP-9, might play important role in pre-metastatic niche formation through facilitating angiogenesis and tumor cell invasion." (PMID 35004667, 2021). "During cellular stress, S100A8 and S100A9 is released as a heterodimer (e.g., calprotectin) into the extracellular space where it binds to TLR4 and initiate a signaling cascade that regulates inflammation, cell proliferation, differentiation, and tumor development in an NF-κB-dependent manner." (PMID 33679877, 2021). "Interestingly, even though Colon-26MGS had higher metastatic abilities, there was no change observed for S100A8 expression in the lungs by transplantation compared to tumor-free mice." (PMID 32325684, 2020). "Notably, knockdown of S100A8 and S100A9 significantly reduced tumor growth in nude mice." (PMID 32503348, 2020). "S100A8/9 boosted migration and proliferation in cells with or without Smad4 tumor cells." (PMID 33117687, 2020). "Additionally, tumor growth in a mouse model was significantly reduced in the absence of S100A8 and S100A9, respectively, thereby emphasizing the impact and pathophysiological relevance of our findings." (PMID 32503348, 2020). "But, tumor cells with transient decrease of Smad4 do not react to S100A8, but not S100A9." (PMID 33117687, 2020).
tumor (continued). "Additionally, S100A8/A9 interaction with RAGE activates NF-κB and MAPK signalling, leading to upregulation of chemokines, such as CXCL1, CLC5, and CLC7, resulting in the formation of a premetastatic niche and tumour progression." (PMID 32722137, 2020). "As we establish, higher expression of S100A8 and S100A9 is indicative of the presence of pro-tumorigenic microenvironment and also predict prognosis, their expression levels in the post-operative tumor have the possibility to serve as a biomarker for predicting survival." (PMID 30808902, 2019). "Moreover, we observed that the number of S100A8-positive monocytes was significantly lower in tumours which lacked Smad-4, suggesting a paracrine interaction between tumour cells and the monocytic stromal compartment." (PMID 30558665, 2018). "Likewise, our analysis revealed an upregulation of genes S100A8 and S100A9 which have previously been reported as salivary biomarkers of OSCC, whose expression has been shown to induce tumor-infiltrating monocytes and macrophages leading to increased cancer cell invasion and metastasis." (PMID 30018735, 2018). "Since the gMDSCs derived from metastatic 4T1 tumour-bearing animals were able to suppress the EMT-related genes and also induce distinct set of genes; S100A9, MMP8, S100A8, WFDC21, LYZ2, FPR1, CCL3, TGFb2, we reasoned whether these genes could be specific for metastatic/aggressive behaviour." (PMID 28382931, 2017). "After intravasation, most of tumor cells in circulation are damaged by the shear stress and mechanical stresses in blood, thus releasing intracellular molecules, many of which have been identified as the ligands for TLR2/4, including HMGB1, HSP60, HSP70, gp96, S100A8, S100A9, SAA3 and so on." (PMID 28415700, 2017). "On the other hand, before tumor arrival in the metastatic sites, the primary tumor also produces systemic factors, for example, VEGFA, TGFβ, TNF, and LOX, which induce chemotactic protein expressions like S100A8, S100A9, SAA3 and extracellular matrix remodeling." (PMID 29450136, 2017). "In the present study, we demonstrate that B16 cells (a mouse melanoma tumor line) expressing recombinant sCRT39-272 exhibit significantly more malignant behavior in mice, which is attributed to the ability of sCRT39-272 to expand and recruit MDSCs in a TLR4 and S100A8/9-dependent manner." (PMID 29075268, 2017). "Thus, sCRT39-272 could directly interact with MDSCs derived from tumor-bearing animals through TLR4, leading to production of S100A8/9, which in turn blocks MDSC differentiation." (PMID 29075268, 2017). "Heterocomplex of S100A8/S100A9 can influence migration of MDSC and may induce tumour cell invasion." (PMID 26880885, 2016). "However, in the present study, S100A8 and S100A9 did not exhibit an association with RCC tumor grades." (PMID 25673070, 2015). "Integrated genomic analysis of microarray data from primary tumours of the two different isogenic pairs revealed that MMP-3, Pthlh and S100a8 were commonly upregulated and that Cd36 was commonly downregulated, indicating that these genes might be causal in tumour cell dissemination." (PMID 25633981, 2015). "Extracellular S100A8 and S100A9 in tumor microenvironment may mainly exert their biological roles in CRC progression, and their secretion to tumor microenvironment may be affected by a variety of factors including tumor cells, stromal cells, and other composition of the tumor microenvironment." (PMID 23637971, 2013). "Interestingly, tumor-induced up-regulation of S100A8 and S100A9 proteins were found in myeloid precursor cells and have contributed to the recruitment and accumulation of myeloid-derived immune-suppressor cells at sites of tumor formation." (PMID 23613688, 2013). "Furthermore, over-expression of S100A9 or S100A8/A9, but interestingly not S100A8, promoted tumor growth and MDSC development in parallel." (PMID 22470535, 2012).
tumor (continued). "Interestingly enough, those authors showed that the promotion effect of low concentrations of S100A8/A9 on tumor cells proliferation was mediated by the RAGE-NFκB pathway, a pathway that was proposed in other studies to mediate the pro-apoptotic effect of S100A8/A9." (PMID 22685372, 2012). "In tumor‐bearing mice, both tasquinimod treatment and CD300ld gene knockout inhibited PMN‐MDSC migration and reduced immunosuppressive effects, suggesting that drugs targeting CD300ld could exhibit comparable antitumor efficacy to those targeting S100A8/S100A9." (PMID 40452814, 2025). "Recently, researches have demonstrated that S100A8 and S100A9 dimers could interact with multiple receptors like RAGE (receptor for advanced glycation end products), TLR (toll-like receptor) and Wnt/β-catenin to promote tumor developments and invasiveness 58-60." (PMID 36046652, 2022). "However, altogether intracellular and/or extracellular S100A8/A9 dimers seems to deeply impact non-parenchymal cells in the tumor microenvironment and hepatocytes to in fine exacerbate proliferation and migration/invasion features of transformed cells, thus promoting tumorigenesis and malignancy." (PMID 36232334, 2022). "Besides, expression of S100A8/A9 in endothelial cells and myeloid in premetastatic organs in response to transforming growth factor β, tumor necrosis factor α (TNFα), and VEGF expressed by distal primary tumors promotes homing of tumor cells to premetastatic niches." (PMID 33117687, 2020). "The absence of S100A8/A9 could significantly reduce the tumor size in HCC model." (PMID 27216119, 2016). "Therefore, S100A8/A9 may be provided by myeloid cells including neutrophils but not by tumor cells in ESCC tissues." (PMID 26625258, 2015). "Again, S100A8/A9 stimulation did not reverse this effect, indicating that MCAM is essential for tumor-promoting responses to extracellular S100A8/A9 in GC cells." (PMID 40924339, 2025). "For both the in vivo tumor challenge experiment and the in vitro migration assay, we utilized recombinant S100A9 protein and not S100A8 or heterodimeric S100A8/A9." (PMID 39497822, 2024). "Among the genes upregulated in the tumor compartment (79 PanCK+ segments from 10 patients) of non-responders, the most differentially expressed were IDO1, HLA-F, S100A8, and S100A9." (PMID 37835599, 2023). "The performance of the models for lower grade cancer is not surprising given the roles of S100A8 and S100A9 in recruitment of immune cells essentially prepping the tissue for tumor formation." (PMID 36284356, 2022). "There was a remarkable and significant increase of positive IRS regarding the tumor center compared to the invasion front for both HPV+ (p = 0.0093) and HPV− (p = 0.0013) PeCa for the Calprotectin subunit S100A9 but not for S100A8." (PMID 36303837, 2022). "Interestingly, our ex-vivo studies showed that S100A8 is a potent activator of NK cells, as indicated by increased expression of granzyme B, thus it is plausible that treating tumor-bearing mice with S100A8 may induce activation and function of NK cells without altering their numbers." (PMID 35655772, 2022). "Among low molecular weight proteins visualized, S100A8 and S100A9 were found to be expressed in the regions of tumor tissue but not in the surrounding healthy stroma of a post-operative microdissected tissue." (PMID 32733643, 2020). "Given some expression of S100A8 and S100A9 in the tumor stroma and the distant healthy epithelium, these regions proved not to be clearly distinguishable from the tumor." (PMID 32733643, 2020). "In particular, we noted that S100A8 and S100A9 transcript levels in GBM have a significant, positive, high correlation with stromal scores and a significant, negative, correlation with tumor purity score." (PMID 30808902, 2019). "The mRNA levels of RBL2 (P=0.2687), SASH1 (P=0.0859), S100A8 (P=0.2198) and S100A9 (P=0.0731) were not significantly different between ER+-cancer tissues and ER+-tumor-adjacent tissues." (PMID 29416786, 2018).